COL6A4P1 (collagen type VI alpha 4 pseudogene 1 )
Synonyms: COL6A4; COL6A4P; DIVA; DVWA; FAME3; VWA6
Gene: Long non-coding RNA gene on chromosome 3 (15,165,275 to 15,205,959, reverse strand). Ensembl gene ENSG00000291281.
Diseases named in the same sentence as COL6A4P1 in open-access papers:
COL6A4P1 is named in the same sentence as 1 disease in open-access papers, as found by Europe PMC text mining. Sharing a sentence is not in itself a finding about the gene and the disease.
COL6A4P1 shares sentences with these, for which no sentence is quoted: tumours (1 paper).